APC (APC regulator of Wnt signaling pathway)
Diseases named in the same sentence as APC in open-access papers (continued):
Sharing a sentence is not in itself a finding about the gene and the disease.
adenoma (continued). "Since our strategy is to block Pol-β activity by small molecular compounds and increase the efficacy of TMZ, it will also benefit patients who carry wild-type or mutant APC gene; the mutant APC gene is the precursors of adenomas and carcinomas in familial adenomatous polyosis (FAP) colon cancer." (PMID 21311763, 2011). "Recently, it was shown that β-catenin stabilization and C-terminal binding protein 1 (CtBP1) following APC inactivation contribute to adenoma initiation as the first step, and that KRAS activation and β-catenin nuclear localization act synergistically to promote adenoma progression to carcinoma." (PMID 24212796, 2011). "In a single adenoma, APC as well as CTNNB, and in two adenomas APC as well as K-Ras, were altered." (PMID 24212608, 2010). "Analysis of the APC inactivation status in the adenomas and adenocarcinomas detected in our patients may help to better understand the mechanism of the involvement of APC mutations in tumorigenesis." (PMID 21078199, 2010). "In a single adenoma, three genes (APC, K-Ras and CTNNB1) were found to be altered." (PMID 24212608, 2010). "Codon 1465 of the APC gene (deletion of an AG) was found to be modified in one serrated lesion and in two adenomas, while an insertion of a single A in codon 1556 was detected in two adenomas." (PMID 24212608, 2010). "The APC p.Glu1317Gly variant appeared to influence the adenoma growth (P = .04, exact test) but not its occurrence." (PMID 19888426, 2009). "This applies both to studied Polyposis patients with <100 adenomas as well as to Polyposis patients with >100 adenomas, who are also negative for APC germline mutations." (PMID 19506731, 2008). "When cases were divided based on APC truncation mutation status, an association was detected in adenomas without APC mutation in relation to "ever smoking", with an OR = 3.97 (1.26–12.51)." (PMID 16545110, 2006). "Interestingly, while APC mutated mice develop low-grade adenomas, the development of tumours in the APC/netrin-1 mice was pushed towards high-grade adenoma and adenocarcinoma." (PMID 15956977, 2005). "They concluded that new APC mutations are acquired at the time point representing malignant transformation during the development of nonpolypoid adenomas." (PMID 15213719, 2004). "Thus, APC gene alterations in patients with FAP may contribute to conventional adenomas and neuroendocrine differentiation within these lesions, thereby broadening the potential scope of impact of APC on FAP-related neoplasia." (PMID 40491286, 2026). "For those cases (with at least 20 adenomas), in which no germline variant in one of the known polyposis genes could be identified, it is recommended to include APC mosaic analysis in routine diagnostic workflows." (PMID 40237877, 2025). "Since APC and KRAS are the most frequently mutated driver genes in the adenoma-to-carcinoma sequence, they could be expected to demonstrate alterations more frequently; moreover, the MUC6 and MUC3A mutations were the most frequent, followed by KRAS mutations, principally in TAs and VAs/TVAs." (PMID 40002249, 2025). "Even though this study did not assess lipidomic changes in human tumor tissues according to the APC status and staging, the additional quantitative lipidome analysis was performed on adenomas from Apc1638N mice to test whether deregulation of TG species is conserved in mice." (PMID 38590663, 2024). "All the analyzed adenomas showed only variants of unknown significance in addition to the inactivating mutations of the APC genes regardless of the number of HCAs in the patients." (PMID 37872280, 2024).
adenoma (continued). "Patients under 60 years with 10 or more adenomas, and those over 60 with 20 or more adenomas or 10 or more adenomas with a family history of adenomas or CRC but without pathogenic variants in APC or MUTYH are categorized as having “multiple colorectal adenomas”." (PMID 39057027, 2024). "In two patients, the adenomas showed moderate immunoreactivity against serum amyloid A. Consistent with the diagnosis of FAP, molecular profiling revealed a pathogenic germline mutation of the APC gene in all analyzed adenomas as well as deleterious somatic second hits." (PMID 37872280, 2024). "The VAFs associated with PIGA variants in this study suggest that the variants may arise early in duodenal adenoma development in a proportion of already initiated adenomas, perhaps following APC initiating events but preceding those affecting other known tumor drivers such as KRAS." (PMID 38546397, 2024). "This may provide the background for an early onset of adenoma formation in APC-Cldn1 mice." (PMID 37627123, 2023). "Therefore, the same group performed a first clinical study using NIR-labeled anti-VEGF-antibodies for the endoscopic detection of CRC precursors in patients with familial adenomatous polyposis, a hereditary disease causing high adenoma and CRC incidence due to a mutation in the APC gene." (PMID 35280747, 2022). "Indeed recent studies show that BCL-2 is downregulated upon APC mutation and inhibition of Bcl-XL was shown to impair adenoma outgrowth, although BCL-XL inhibition was not effective on preexisting adenomas." (PMID 36860494, 2022). "Interestingly, deletion of Jag1—but not the canonical Notch effector Rbpj—in APC-deficient Lgr5+ cells disrupted the Paneth-cell tumour niche and compromised adenoma growth, suggesting non-canonical Notch signalling as a prospective therapeutic target." (PMID 33673710, 2021). "Since we observed a downregulation of β-catenin only in invasive (metastatic) SW480 and HCT-116 cells and the tumor produced from APC Min/+ mice is a benign adenoma, β-catenin may be a target of sorghum bran extracts only for invasive and metastatic cancer, but not in benign polyps." (PMID 34361052, 2021). "However, in FAP adenomas the Wnt/β-Catenin mediated regulation of ARC expression might be of particular relevance, as β-Catenin is accumulated due to its APC-mutation reasoned missing degradation." (PMID 33579312, 2021). "The first multi-step model of CRC carcinogenesis considered adenomatous polyposis coli (APC) gene inactivation as the initial step followed by KRAS gene mutation and chromosome 18q loss of heterozygosity that further promotes the growth of precancerous adenomas." (PMID 33467526, 2021). "However, numerous studies have indicated that mutation of BRAF is almost never identified in such APC mutated adenomas, even when they develop advanced histological features." (PMID 32384699, 2020). "The inactivating mutations of APC could initiate a benign adenoma by activating the WNT pathway, which was proved by the upregulation of β-catenin driven by APC mutations." (PMID 32117908, 2020). "However, our positive data may suggest that in APC min/J mice adenomas development the EphAs signaling could have a more prominent role than EphBs signaling at least in the earliest phase of the tumor development." (PMID 32316101, 2020).
adenoma (continued). "There is evidence to show that the variation in FAP severity (which have been shown to be independent of APC mutations and most likely the action of modifier alleles), is expected to result in different rates of adenoma number rather than differences in tumour progression." (PMID 28331556, 2017). "Therefore, we next asked whether we could protect wild-type tissue from elimination induced by APC−/− adenomas by expressing inhibitors of apoptosis." (PMID 26853366, 2016). "Importantly, this was not caused by a detrimental effect of Yki activity on APC−/− adenomas, because autonomous overexpression of Yki in APC−/− cells did not inhibit their growth." (PMID 26853366, 2016). "Firstly, in a large proportion of patients with less than 100 adenomas, genetic analysis of the germline mutations APC and MYH is not conclusive, which results in a diagnosis of adenomatous polyposis of unknown origin." (PMID 27821077, 2016). "Moreover, nuclear β-catenin accumulation is observed in an important fraction of intramucosal tumors and invasive cancers but not in adenomas carrying APC mutations." (PMID 26631503, 2015). "In addition to the APC/Wnt pathway known to be involved in the development of the colorectal adenoma, this study has identified a few new cellular pathways that are altered in the adenoma at the genetic level." (PMID 23301059, 2013). "Previously reported genetically engineered mouse modelsthat mimic human APC gene mutations mainly develop adenomas in thesmall intestine (e.g. ApcMin model), rather than thedistal colon, making it difficult to image the progression of polyps invivo using small animal endoscopy." (PMID 21408169, 2011). "The morphology of the adenomas appears to be similar regardless of whether their occurrence is caused by germline mutations in the MUTYH or in the APC gene." (PMID 19506731, 2008). "A recent study of CRC has identified the APC oncogene to contain the highest number of pks motifs, whilst the KRAS gene, also characteristic of the conventional adenoma-carcinoma pathway and CMS3 subtypes, contained the fourth highest number of pks motifs." (PMID 39340753, 2024). "Incident cancer may represent a distinct early event, in which MMR-D commonly precedes APC mutations and the endoscopic removal of precursor lesions during surveillance may be more effective in preventing KRAS-mutated lesions, since KRAS mutations are associated with conventional adenomas." (PMID 37568596, 2023). "In this sense, disruption of the RNF43–ZNRF3 axis in the serrated pathway may serve similar, but not identical, functions to the APC mutations do in the adenoma–carcinoma pathway, which may have implications for the therapeutic targeting of the Wnt pathway in different CRC subtypes." (PMID 35975243, 2022). "In most cases, biallelic inactivation of APC is the culprit for CRC occurrence and it plays a key role in tumor progression to adenomas by activating responsible pathways." (PMID 35223868, 2021).
adenoma (continued). "Other works analyzing AAP cohorts, such as Grover30 who analyzed MUTYH and APC in 4223 patients with 10 to 100 adenomas, or Stanich20 who also analyze POLD1 and POLE and other CRC genes in 2979 patients with 10 to 100 adenomas, showed similar clinical results." (PMID 31285513, 2019). "Nevertheless there is an earlier study on plasma methylation of RASSF2A, APC, MGMT and Wif-1 that suggested a more promising biomarker panel for adenoma with sensitivity of 86.5% and specificity of 92.1%." (PMID 29765549, 2018). "To address the molecular mechanisms by which the PID repressed proliferation and tumorigenesis in mice, we established 6 primary colonic cell lines from adenomas from both cohorts (CDX2;APC;PID and CDX2;APC, 3 cell lines for each genotype)." (PMID 30150766, 2018). "Our HGCA mutation list includes not only those in this classical model (APC and KRAS) but also those already known as adenoma genes (NRAS and GNAS)." (PMID 28179590, 2017). "Genetic transformation of mutant APC in FAP results in abnormal CRC cell proliferation, leading to the outgrowth of numerous adenomas in the colons of patients." (PMID 28331559, 2017). "However, none of them except APC are anticipated to be frequently mutated in the adenoma." (PMID 23301059, 2013). "Furthermore, the fact that about half of the x-ray induced intestinal adenomas in APCMin/+ mice arise without LOH and most of the adenomas are polyclonal supports the notion that not all the intestinal tumors results from functional APC loss mediated β-catenin stabilization." (PMID 23555653, 2013). "Notably, although BMDCs were found incorporated into the intestinal adenoma in APC-mutated multiple intestinal neoplasia mice, none of adenomas ubiquitously consisted of BMDCs, suggesting that the mechanism by which BMDCs contribute to pathogenesis was not likely to be cell fusion." (PMID 22291966, 2012). "The observed expression of the locus in Min-induced adenomas is consistent with the bioinformatic prediction of WNT-induced transcription from the strong upstream promoter P1 and the known action of APC protein to regulate WNT signaling." (PMID 22670227, 2012). "In particular for the APC model, it has been shown that deletion of APC specifically in LGR5-positive cells is sufficient to give rise to adenomas within 3–5 weeks." (PMID 22848656, 2012). "For APC, the MCR was successfully sequenced and analyzed for 155 adenomas, i.e. 81 polypoid adenomas and 74 flat adenomas." (PMID 22848674, 2012). "This APC mutation is present in approximately 85% of non-hereditary CRC cases and plays a critical role in initiating the adenoma–carcinoma sequence." (PMID 40310348, 2025). "As APC is integrally involved in the development of adenomas by both germline and somatic inactivation, RNF43 defects could promote the formation of adenomas." (PMID 38725616, 2024). "Unlike the classic adenoma-carcinoma sequence, where APC inactivation is the initiating event, the serrated pathway is driven by BRAF mutations, with serrated polyps serving as the precursor lesions." (PMID 39119381, 2024). "A systematic review published by INCISE identified 49 gene mutations, single nucleotide polymorphisms, or haplotypes in 23 different genes/chromosomal regions (including KRAS, APC, EGFR, and COX1/2) that predicted metachronous adenoma or advanced adenoma development." (PMID 37158435, 2023).
adenoma (continued). "But nuclear β-catenin is not frequently observed in early adenomas that form in FAP patients, sporadic human colonic polyps, or microadenomas from a rat FAP model, despite confirmed loss of heterozygosity of APC and increased cellular levels of β-catenin." (PMID 37759479, 2023). "Genetic analyses of IPMNs among FAP patients have reported an absence of the APC protein that is typical of the adenomas in FAP patients elsewhere." (PMID 35884779, 2022). "In one study including two foveolar adenomas of the duodenum, both harbored GNAS mutations, while no APC, KRAS, or CTNNB1 mutations were found." (PMID 33922305, 2021). "During CRC-initiation, the length and hence the functionality of truncated APC, which translates to different doses of oncogenic Wnt activity, influences the level of LARGE2 expression and the O-glycosylation status of α-DG in human adenoma organoids." (PMID 32586342, 2020). "Surprisingly, when the APC gene is excluded, one gene with frequent accumulating genomic alterations CCR4-NOT Transcription Complex Subunit 3 (CNOT3), which was observed in 5 out of 25 sequenced FAP adenomas." (PMID 31231471, 2019). "Several studies have demonstrated that adenomas should be included in the screening for low level APC mosaicism as a high frequency of cases are not detectable in leukocyte DNA." (PMID 29368261, 2018). "Thus, NOTCH activation alone in intestinal cells was unable to induce adenoma formation, but overexpression of activated NOTCH promoted adenoma formation and decreased the survival of an APC+/− mouse model." (PMID 29652830, 2018). "Interestingly, the number of adenomas was 40 and 65% less in small and large intestine in CDX2;APC;PID mice, respectively." (PMID 30150766, 2018). "Several studies have failed to correlate the lack of APC with activation of the Wnt pathway as determined by the presence of nuclear β-Catenin, especially in early adenomas." (PMID 28331559, 2017). "Secondly, compared with non-carriers, APC I1307K carriers had increased numbers of adenomas and tumors per patient, as well as younger age at diagnosis." (PMID 27595705, 2016). "The expression of APC was positive in control samples but not in the three affected individuals, both in adenoma and adenocarcinoma tissues, supporting the prediction that the truncated APC protein in the affected individuals lacks the C-terminus." (PMID 27000756, 2016). "Concurrent with the formulation of the adenoma-carcinoma sequence in sporadic tumours, fine mapping of genomic lesions in the germline of patients with familial adenomatous polyposis (FAP) syndrome has pointed at the same APC gene." (PMID 27279102, 2016). "Analysis of the common insertion sites for transposon in neoplasms, adenomas and adenocarcinomas revealed that 80% of insertions fell in known CRC genes including APC, FBXW7 (F‐box and WD repeat domain containing 7), PTEN (phosphatase and tensin homolog), and SMAD4, thus validating the approach." (PMID 26115037, 2015). "ESR1 has been shown to occur in histologically normal colon epithelium in an age dependent fashion, CDH13 is also frequently methylated in CRC and seems to be correlated with the adenoma-carcinoma transition, like other genes with methylation frequencies > 30% (CDKN2B, RASSF1, RARB, APC and TIMP3)." (PMID 25091577, 2014).